EZH2 (enhancer of zeste 2 polycomb repressive complex 2 subunit)
Diseases named in the same sentence as EZH2 in open-access papers (continued):
Sharing a sentence is not in itself a finding about the gene and the disease.
prostate carcinoma (continued). "The overexpression of EZH2 is implicated in aggressiveness and poor prognosis in a wide spectrum of malignancies including cancers of the prostate, breast, female genital tracts, and melanoma." (PMID 36292072, 2022). "EZH2 has been well studied in prostate cancer, and its mutations are the leading cause of the progression of prostate cancer." (PMID 34307682, 2021). "As previously discussed, lower levels of HNF1B in prostate cancer has now been associated with higher EZH2, promoting EMT and metastasis." (PMID 33580750, 2021). "We revealed that the lncRNA SChLAP1 (second chromosome locus associated with prostate-1) promotes prostate cancer development via interacting with EZH2 to promote H2K27me3 and regulate miR-340-5p/miR-143-3p/miR-145-5p expression." (PMID 33589600, 2021). "EZH2 expression is commonly elevated in nearly all solid cancers, including gastric, breast and prostate cancers, which is associated with poor prognosis, suggesting an oncogenic role of EZH2 in these cancers." (PMID 34512145, 2021). "In prostate cancer patients, EZH2 is associated with increased cell proliferation, invasiveness and metastasis." (PMID 33803328, 2021). "In vitro experiments performed in this study suggested that the loss of USP44 reduced both the EZH2 protein levels and oncogenic activity of prostate cancer cells." (PMID 34572834, 2021). "In line with a function in driving disease progression and dedifferentiation towards the loss of AR expression, we demonstrate how EZH2 inhibition reverts the transcriptional output of prostate cancer cells along the progression trajectory." (PMID 34857732, 2021). "The increased EZH2 expression in prostate cancer was to be associated with metastastic recurrence after radiotherapy." (PMID 32922184, 2020). "Among them, miR-124 has been previously shown to target and downregulate Ezh2 mRNA expression during early mouse neurogenesis and let-7, which has been previously associated with Ezh2 mRNA control in prostate cancer cells." (PMID 33187138, 2020). "Overexpression of EZH2 is also associated with the development of prostate cancer, and phosphorylated EZH2 can act as a co-activator of transcription factors, such as promoting the expression of AR41,42." (PMID 32251318, 2020). "Collectively, our findings revealed that thepromotion of the malignancy-associated characteristics of prostate cancer cellsby USP7 was in part due to EZH2 stabilization." (PMID 32453339, 2020). "RB1 loss promotes lineage transformation in prostate cancer via the upregulation of epigenetic and reprogramming factors including EZH2." (PMID 32292420, 2020). "Early evidence has confirmed that the overexpression of EZH2 is associated with the worsening of prostate cancer progression." (PMID 32448308, 2020). "EZH2 overexpression was first identified in prostate cancer and associated with poor clinical outcomes." (PMID 32723346, 2020). "EZH2 expression was investigated using immunohistochemistry in diagnostic prostate biopsies of 113 prostate cancer patients treated with radiotherapy with curative intent." (PMID 31104332, 2019). "In Myc-driven prostate cancers, EZH2 histone methyltransferase expression is induced and causes the repression of Interferon gamma receptor 1, with consequent loss of tumor suppressor signaling and reduced apoptosis due to the activation of this receptor." (PMID 31366128, 2019). "Reduces ARs with the F876L mutation in DU-145 and C4-2 cells, and destroys prostate cancer stem/progenitor (S/P) cell invasion through the alteration of EZH2/STAT3 signaling in mice with CWR-22Rv1 CD133+ S/P xenografts." (PMID 31801262, 2019). "The expression of EZH2 increased in prostate cancer, and its elevation is associated with prostate cancer progression and poor prognosis." (PMID 31366128, 2019).
prostate carcinoma (continued). "A Polycomb-independent (PcI), but still methyltransferase-dependent function of EZH2 is also implicated in prostate cancer progression 13, suggesting that EZH2 is a viable therapeutic target." (PMID 31410199, 2019). "The overexpression of EZH2 is often associated with cell proliferation and invasiveness in prostate cancer." (PMID 31410199, 2019). "Reduces ARs with the F876L mutation in DU-145 and C4–2 cells, and destroy prostate cancer stem/progenitor (S/P) cell invasion through the alteration of EZH2/STAT3 signaling in mice with CWR-22Rv1 CD133+ S/P xenografts." (PMID 31801262, 2019). "Our findings suggest that EZH2 repression of expression of the FOXO1 tumor suppressor can be targeted by EZH2 inhibitor as a monotherapy for PTEN-proficient cancers or in combination with taxane for treatment of PTEN-deficient prostate cancers." (PMID 31410199, 2019). "The significance of EZH2 in cancer was firstly realized in 2002 when Varambally and colleagues elucidated the association betweenEZH2 and prostate cancer prognosis." (PMID 29556394, 2018). "EZH2 expression increases throughout prostate cancer progression and EZH2 expression levels are associated with methylation level in prostate cancer." (PMID 28412973, 2017). "EZH2 is highly overexpressed in prostate cancer and strongly associated with epigenetic silencing in cancer." (PMID 28403887, 2017). "Both MYC and MYCN directly upregulate enhancer of zeste homolog 2 (EZH2) which is linked to prostate cancer progression." (PMID 28212321, 2017). "High expression of the EZH2 gene is also associated with low MSMB levels in metastasizing prostate cancer." (PMID 28410242, 2017). "Since then, many studies have highlighted the association between EZH2 expression and prostate cancer development." (PMID 28410242, 2017). "The RUNX1 expression level in clinical prostate cancer tissues is negatively associated with EZH2 expression, and decreased RUNX1 expression is correlated with poor prognosis." (PMID 28264478, 2017). "The earliest and intensive study of a role for EZH2 in cancer was that EZH2 overexpression was associated with worse progression of prostate cancer." (PMID 27835578, 2016). "Using a cut-off of ≥ 1% in radical prostatectomy specimens, we found that EZH2 expression was associated with high-grade prostate cancer and biochemical recurrence." (PMID 27191985, 2016). "Expression of EZH2, which functions as an epigenetic gene silencer, increases in prostate cancer and it plays an oncogenic role in prostate cancer that is typically associated with increased risk of metastasis and recurrence." (PMID 27191265, 2016). "EZH2 is an important methyltransferase that is frequently overexpressed in breast and prostate cancers and is associated with tumor growth and invasion." (PMID 26038315, 2015). "Hyperactivation of EZH2, by amplification/overexpression or mutation, was documented in breast and prostate cancers, lymphoma, and other types of tumors." (PMID 25537518, 2015). "The finding that the predicted upstream regulatory genes included HIF1A, WT1, and EZH2 genes, reported to be associated with prostate cancer metastasis, suggests that the approach used had merit." (PMID 24448395, 2014). "A number of studies support the role of EZH2 as an oncogene in prostate cancer that is typically associated with increased risk of metastasis and recurrence." (PMID 25115397, 2014). "Many authors have demonstrated that overexpression of EZH2 was strongly associated with progression and invasion of prostate cancer." (PMID 25535400, 2014). "For example, overexpression of EZH2 is associated with many different tumors, including breast and prostate cancer." (PMID 24782528, 2014). "mir-101 reportedly targets EZH2, and the genomic loss of mir-101 leads to the overexpression of EZH2 in prostate cancer cells." (PMID 24348521, 2013).
prostate carcinoma (continued). "These analyses showed that LXRβ expression was significantly down-regulated in prostate carcinomas compared to normal tissue and that this down-regulation was associated with increased EZH2 expression." (PMID 23675307, 2013). "Further study into specific mechanisms of action of EZH2 have linked it with the gene fusion found in 50% of prostate cancers of TMPRSS2, an androgen-regulated gene, and the oncogenic ETS transcription factor ERG." (PMID 22641253, 2012). "For instance, loss or knock-down of PcG protein Ezh2 causes loss of cell growth and the transformed phenotype of prostate cancer cells." (PMID 22292011, 2012). "The polycomb protein EZH2 is emerging to be a key driver for tumor formation and has been implicated in prostate cancer metastasis." (PMID 23251464, 2012). "Gain of function mutation of EZH2 and deletion of a microRNA, a negative regulator of EZH2 expression, have been linked to lymphomas and prostate cancer." (PMID 21886846, 2011). "Involvement of repressive epigenetic programs via a Polycomb group of proteins, H3K27 methyl transferase EZH2, also has been demonstrated, which helps us understand the mechanism underlying progression of prostate cancer." (PMID 24213111, 2011). "Numerous studies indicate that Ezh2 overexpression is a common phenomenon in prostate cancer (PCa) that is associated with a poor clinical outcome of PCa patients." (PMID 20478051, 2010). "Previous work has shown that EZH2 was significantly upregulated and associated with high proliferation rate and aggressive tumor subgroups in prostate cancer." (PMID 19262738, 2009). "Expression of all three proteins (BMI1, RING1, and EZH2) is associated with adverse pathological features in prostate cancer, but only BMI1 provides additional prognostic power in multivariate analysis." (PMID 19002169, 2009). "One of the target genes for EZH2 in prostate cancer cells is DAB2IP, whose encoded protein is a potent cell growth inhibitor and modulator of Ras-signalling." (PMID 19002169, 2009). "In breast and prostate cancers, EZH2 over-expression is linked to aggressive tumor formation and poor prognosis and in a subset of cancers, the EZH2 locus is amplified resulting in EZH2 over-expression." (PMID 18980680, 2008). "Gain-of-function mutations or loss-of-function mutations may occur in EZH2, and both mutation type was involved in the development of prostate cancer." (PMID 40959108, 2025). "Based on its important role in differentiation, we hypothesized that EZH2 would have variable functions in prostate cancer depending on the underlying differentiation state or phenotype." (PMID 38405800, 2024). "However, one gene implicated in various aspects of prostate cancer progression is EZH2 (enhancer of zeste homologue 2)." (PMID 37104245, 2023). "EZH2 has been shown to play a causal role in driving prostate cancer development and progression, by suppressing key PRC2 target genes, some of which are known and many others which are likely unknown." (PMID 37104245, 2023). "Enhancer of zeste homolog 2 (EZH2), one of the histone methyltransferase enzymes, is associated to the expansion, migration, and invasion of malignant cells, such as glioblastoma, ovarian, and prostate cancer." (PMID 37038154, 2023). "Silencing SNHG1 or EZH2 is associated with decreased viability of prostate cancer cells." (PMID 35317831, 2022). "While the methyltransferase has been associated with oncogenic properties in, e.g., lung- and prostate cancer, glioblastoma, or lymphoma, tumor-suppressive EZH2 activities have been revealed for T-cell acute lymphoblastic leukemia, clear cell renal carcinoma, or colorectal cancer." (PMID 35884510, 2022). "The association of EZH2 overexpression with both gene-specific and global hypermethylation has been described before for prostate cancer, small cell lung carcinoma and cell sarcoma of the kidney, suggesting the role of this histone modifier in directing hypermethylation." (PMID 34208581, 2021).
prostate carcinoma (continued). "Dysregulation of EZH2 was first linked to cancer by performing gene expression profiling in prostate cancer, which showed EZH2 is involved in prostate cancer progression, and its expression distinguishes indolent forms of prostate cancer from those forms at risk of lethal progression." (PMID 34376807, 2021). "Studies have shown associations between EZH2 and poor prognosis in prostate cancer." (PMID 33050946, 2020). "The initiation and evolution of prostate cancer is associated with overexpression of Myc and EZH2." (PMID 31886200, 2019). "In prostate cancer, there is a positive feedback mechanism between Myc and EZH2, where Myc overexpression is associated with increased EZH2 and EZH2 could also induce Myc overexpression." (PMID 31886200, 2019). "In summary, our data describe the impacts of JMJD3 and EZH2 on a new gene signature involved in prostate cancer that may help identify diagnostic and therapeutic targets in prostate cancer." (PMID 29805743, 2018). "Furthermore, TOP2A expression has been previously linked to EZH2 expression in aggressive prostate cancer." (PMID 29200404, 2018). "Xu and colleagues demonstrated that EZH2 acts as a coactivator of androgen receptor-associated complexes to support castration-resistant prostate cancer (CRPC) growth, suggesting novel combination therapies for the treatment of metastatic, hormone-refractory prostate cancer." (PMID 29556394, 2018). "Nearly all high‐risk prostate cancer samples in this study expressed EZH2." (PMID 26471467, 2015). "Indeed, EZH2 acts mainly as a gene silencer in the progression of cancers such as breast and prostate cancer, and the overexpression of EZH2 is associated with aggressive and metastatic disease." (PMID 25084021, 2014). "In a set of 86 needle-biopsies of screen-detected low-risk prostate cancer, EZH2 expression >1% was associated with clinically significant tumors on radical prostatectomy, defined as presence of extraprostatic extension, Gleason grade 4/5 or tumor volume ≥0.5 mL." (PMID 25243131, 2014). "The aim of this study was to assess the association between H3K27me3 level and prostate cancer risk and the correlation of H3K27me3 on EZH2, RAR beta 2, ER alpha, PGR, and RGMA promoters with clinicopathological variables including Gleason score, PSA levels and clinical stages." (PMID 25535400, 2014). "PAH and cancer cells share similar proliferating phenotypes, and the overexpression of EZH2 is directly responsible for the de novo suppression of multiple genes in human cancer and is a known pathogenic factor in breast and prostate cancer." (PMID 22662197, 2012). "Overexpression of EZH2 has been associated with the invasion and progression of prostate cancer." (PMID 22191037, 2011). "We hypothesize that the AR/DPYSL5/EZH2/PRC2 axis is a novel mechanism underlying prostate cancer progression to t-NEPC, and it is important to further elucidate the theranostic potential of DPYSL5 and explore any pharmacological strategies that could manipulate its expression." (PMID 38238517, 2024). "An increase in the expression of EZH2 is associated with increased proliferation, migration, and invasion of cancer cells in various types of cancer: hepatocellular carcinoma, ovarian carcinoma, gastric cancer, laryngeal squamous cell carcinoma, and prostate cancer." (PMID 36362406, 2022). "Consequently, Rb1 loss in prostate cancer lead to EZH2 and Sox2 increase and gene expression widespread changes that leads toward a stem cell-like state that would facilitate the onset of metastasis, neuroendocrine transdifferentiation, and the acquisition of ADT resistance." (PMID 29888169, 2018). "Hence, EZH2 is considered a potential diagnostic and prognostic biomarker in prostate cancer." (PMID 28410242, 2017). "However, the roles and underlying mechanisms of EZH2 in prostate cancer stem cells (PCSCs) remain unknown." (PMID 23739676, 2013).
prostate carcinoma (continued). "Interestingly, a recent study demonstrated that loss of let-7 up-regulates EZH2 in prostate cancer with the acquisition of cancer stem cell signatures, suggesting that let-7 functions to promote cell differentiation through repression of EZH2 in prostate cancer." (PMID 23717621, 2013). "Here, we report that, in prostate cancer (PCa), Polycomb group (PcG) protein Enhancer of Zeste Homolog 2 (EZH2) exerts an additional function in m6A regulation via its enzymatic activity." (PMID 41252201, 2026). "For instance, miR-101, miR-26a, and miR-26b —known to suppress EZH2—are significantly downregulated in prostate cancer 61-63." (PMID 40959108, 2025). "In summary, SETD2 and EZH2 play distinct but critical roles in prostate cancer development, progression, and metastasis." (PMID 40959108, 2025). "On the other hand, co-targeting of the epigenetic regulators EZH2 and HDACs has been shown to be more cytotoxic than either treatment alone against castration-resistant prostate cancer." (PMID 41007839, 2025). "This parallel underscore the potential significance of epigenetic regulation, particularly involving SUZ12 and EZH2, in contributing to prostate cancer disparities among different racial groups." (PMID 40104216, 2025). "Specifically, prostate cancer organoids cultured in Arg-Glu-Asp-Val (REDV)-functionalized hydrogels showed reduced actin symmetry under enhancer of zeste homolog 2 (EZH2) inhibition, illustrating ECM-dependent drug responses." (PMID 41155895, 2025). "EZH2 is often overexpressed in various cancers, including lymphoma, prostate cancer, and breast cancer, and UNC1999 works by restoring the expression of tumor-suppressor genes, thus inhibiting cancer cell proliferation." (PMID 41335282, 2025). "Their research revealed that EZH2 upregulation correlates with advanced disease stages and poor outcomes in prostate cancer." (PMID 40004468, 2025). "SETD2 and EZH2 are two important members of HMTs, and plays important roles in prostate cancer progression and metastasis." (PMID 40959108, 2025). "In research published in Nature Cell Biology, the authors demonstrated that EZH2 plays a central role in driving lineage plasticity in prostate cancer, promoting neuroendocrine trans differentiation following androgen receptor (AR) inhibition." (PMID 40722714, 2025). "Multi-omics studies have revealed that SETD2 loss induces aberrant DNA methylation and activates oncogenic signaling pathways, whereas EZH2 overexpression cooperates with PI3K-AKT pathway dysregulation to drive castration-resistant prostate cancer." (PMID 40959108, 2025). "EZH2 also contributes to prostate cancer development by directly interacting with AR, enhancing AR activity, and modulating the transcription of its downstream target genes." (PMID 40959108, 2025). "By inhibiting these enzymes, CPI-1205 disrupts the transcriptional silencing of tumor-suppressor genes and inhibits the growth of EZH2-dependent cancers, including lymphoma and prostate cancer." (PMID 41335282, 2025). "EZH2 targeted proteolysis targeting chimera (PROTAC) is a potential attractive therapeutic approach for treating invasive prostate cancer that relies on EZH2 and AR connected circuits." (PMID 41200193, 2025). "PF-06821497 (mevrometostat) effectively inhibits the EZH2 Y641N mutation and is currently being evaluated in a phase III clinical trial for castration-resistant prostate cancer." (PMID 39934895, 2025). "Mechanistically, SETD2 or EZH2 regulate prostate cancer metastasis and drug resistance warrant further study." (PMID 40959108, 2025). "In prostate cancer, both EZH2 and HDAC inhibitors collaboratively suppress the tumor suppressor function of ATF3." (PMID 40659662, 2025). "EZH2 is frequently overexpressed in prostate cancer cells and interacts with several DNA methyltransferases (DNMT1, DNMT3A, DNMT3B), reinforcing its role in epigenetic silencing." (PMID 40959108, 2025).